WASH6P (WASP family homolog 6, pseudogene)
Description:
May act as a nucleation-promoting factor at the surface of endosomes, where it recruits and activates the Arp2/3 complex to induce actin polymerization, playing a key role in the fission of tubules that serve as transport intermediates during endosome sorting.
Synonyms: CXYorf1; FAM39A; WASH
Gene: Protein-coding gene on chromosome X (156,020,826 to 156,025,710, forward strand). Ensembl gene ENSG00000182484.
Subcellular location: Early endosome membrane; Recycling endosome membrane
Subcellular location (Human Protein Atlas): Vesicles
Homologues: Orthologues: macaque WASHC1 (86% identical), dog WASHC1 (80% identical), pig WASHC1 (78% identical), mouse Washc1 (75% identical), rat Washc1 (75% identical), tropical clawed frog washc1 (64% identical), zebrafish wash1 (60% identical), Drosophila melanogaster wash (30% identical), Caenorhabditis elegans ddl-2 (26% identical). Paralogues in human: WASHC1 (87% identical).
Diseases named in the same sentence as WASH6P in open-access papers:
WASH6P is named in the same sentence as 1 disease in open-access papers, as found by Europe PMC text mining. Sharing a sentence is not in itself a finding about the gene and the disease.
WASH6P shares sentences with these, for which no sentence is quoted: cancer (1 paper).